TBP (TATA-box binding protein)
Diseases named in the same sentence as TBP in open-access papers (continued):
Sharing a sentence is not in itself a finding about the gene and the disease.
prostate carcinoma (8 papers, 2007 to 2023). A carcinoma that arises from epithelial cells of the prostate gland. "From the two derived cDNAs, the target gene, encoding PAR1 receptor known to be expressed and regulated in prostate carcinoma and cell lines, was quantified, as well as two dedicated HKGs, namely TBP and PPIA." (PMID 20179706, 2010). "Moreover, TBP has already been used as an RG in several studies on prostate cancer, and in the lymph nodes of a prostate cancer patient, TBP and HPRT1 showed good expression stabilities." (PMID 37558778, 2023). "We have not proved the importance of PA2G4 and Ki67 for CaP detection as they weakly correlated with some prostate cancer-related markers (e.g., AMACR), but also with leukocyte-specific CD45 and house-keeping genes (TBP and RHOA)." (PMID 32630458, 2020). "Whereas in prostate cancer and bladder cancer experiments 13 out of 16 and six out of nine genes, respectively, remained as suitable genes for the further calculations with geNorm and NormFinder, only the two genes PPIA and TBP could be considered for these analyses in the current study." (PMID 17559644, 2007).
autosomal dominant cerebellar ataxia (7 papers, 2014 to 2022). A clinically and genetically heterogeneous group of neurodegenerative diseases characterized by a slowly progressive ataxia of gait, stance and limbs, dysarthria and/or oculomotor disorder, due to cerebellar degeneration in the absence of coexisting diseases. "SCA17 is one of the autosomal dominant cerebellar ataxia by abnormal CAG/CAA repeat expansion encoding a polyQ tract in the TATA-box binding protein (TBP) gene on chromosome 6q27." (PMID 32973440, 2020). "SCA17 is an autosomal dominant cerebellar ataxia with expansion of the CAG/CAA trinucleotide repeats in the TATA-binding protein (TBP) gene." (PMID 26267067, 2015).
glioblastoma (7 papers, 2009 to 2024). The most malignant astrocytic tumor (WHO grade IV). "Johnson and colleagues first discovered that MAF1 binds to the promoter of TATA-binding protein (TBP) gene at the Elk-1 binding motif in glioblastoma for inhibiting Pol II-mediated TBP transcription." (PMID 39363536, 2024). "Previous studies of Maf1 knockdown and overexpression in glioblastoma cells found inverse changes in the expression of the TATA-box-binding protein (TBP) at the RNA and the protein level that correlated with changes in RNA Pol I transcription." (PMID 25934505, 2015). "Altogether, our data show the relevance of previous validation of candidate control genes for each experimental model and indicate TBP plus HPRT1 as suitable references for studies on glioblastoma gene expression." (PMID 19257903, 2009). "For glioblastoma, it was demonstrated that TBP plus HPRT1 are suitable reference genes for normalization purposes in gene expression profiling studies." (PMID 19257903, 2009). "TBP, a key regulator of gene expression, has previously been identified as a suitable RG for expression studies on human hepatitis B virus-related hepatocellular carcinoma, human renal cell carcinoma, and glioblastomas." (PMID 24001041, 2013). "Altogether, the data from many different studies show the relevance of TBP gene expression stability, indicating that it is a suitable reference gene to be used as a control in studies of various kinds of diseases, including some types of cancer such as bladder cancer and glioblastoma." (PMID 38397141, 2024). "Here we show that amongst seven frequently used housekeeping genes TBP and HPRT1 are adequate references for glioblastoma gene expression analysis." (PMID 19257903, 2009).
ovarian carcinoma (6 papers, 2014 to 2024). A malignant neoplasm originating from the surface ovarian epithelium. "Previous studies have reported that under normoxic conditions, the most stably expressed genes in ovarian cancer cells are GAPDH/TBP, while under hypoxic conditions, the most stable candidate housekeeping genes are RPL13A/SDHA." (PMID 38166541, 2024). "The contribution of TFIID stability, presumably regulated by histone-fold dependent association of TAF4 and TAF12, as well as the contribution of putative TFIID sub-complexes that lack TBP or other subunits, merit investigation in the context of ovarian cancer." (PMID 24653979, 2014). "The top 5 related genes are TBP, MMP9, MYC, MAPK1, MTOR, which might play important roles in ovarian cancer." (PMID 32958005, 2020). "Reminiscent of the TFIID-independent function of TAF3 in regulation of myogenesis, the transcriptional control of Inr-containing promoters by TAF1/TAF2 may be relevant in ovarian cancer, since TBP is predominantly downregulated in many HGSCs." (PMID 24653979, 2014). "Lastly, TBP displayed negative correlations with these immune signatures and exhibited a poor prognosis in BRCA and ovarian cancer (OV)." (PMID 39408874, 2024). "BDP1 mRNA expression was significantly decreased in ovarian cancer, p = 0.01 but the expression of other TFIIIB subunits, BRF1, BRF2, and TBP, was not significantly changed." (PMID 36305848, 2023).
Alzheimer disease (5 papers, 2010 to 2022). A progressive, neurodegenerative disease characterized by loss of function and death of nerve cells in several areas of the brain leading to loss of cognitive function such as memory and language. "TBP has also been found in aggregates of Alzheimer’s disease (AD) as well as neuronal intranuclear hyaline inclusion disease (NIH-ID), suggesting that besides its direct involvement in SCA17, TBP is also affected in other neurodegenerative diseases." (PMID 28774347, 2017). "Interestingly, in Alzheimer disease (AD) brain tissue, an N-terminal TBP fragment was also shown to accumulate, whose presumptive origin was linked to a naturally occurring splice variant." (PMID 35482253, 2022).
bladder cancer (5 papers, 2007 to 2024). "As they consistently ranked in the top ten by CoV, GeNorm and Normfinder, UBC, RPLP0, HMBS, GUSB, and TBP are the most suitable endogenous control genes for bladder cancer qPCR." (PMID 33057113, 2020). "Accordingly, seven of the most commonly used reference genes (ACTB, GAPDH, HPRT, B2M, SDHA, TBP, and 18S) were amplified in the three bladder cancer cell lines exposed to normoxia and hypoxia." (PMID 27835695, 2016).
leukemia (5 papers, 2013 to 2022). A malignant (clonal) hematologic disorder, involving hematopoietic stem cells and characterized by the presence of primitive or atypical myeloid or lymphoid cells in the bone marrow and the blood. "One candidate for a chromatin-associated factor interacting with both acetylated histones and the transcriptional machinery (TBP, RNA polymerase II) is Brd2, which was recently implicated in the regulation of STAT5 activity in leukemia cell lines." (PMID 25769527, 2015). "Some top ranked regions suggested co-binding of E2F4 with the core transcriptional machinery such as TBP and Pol2 in lymphoma (CH12 tracks) and leukemia (MEL tracks)." (PMID 27098038, 2016). "qRT-PCR was performed for each of the 14 new genes, as well as for 5 standard control genes (GAPDH, ACTB, TBP, HPRT1, ABL1), on cDNA from a panel of 14 leukemia samples (10 AML, 4 ALL) plus one CD34+ cord blood sample (using equal amounts of RNA)." (PMID 24069164, 2013).
Obesity (5 papers, 2015 to 2026). Accumulation of substantial excess body fat. "Normalizing PGC1α expression data to the least stable RGs (HRPT1/TBP) revealed a different pattern where PGC1α levels were significantly increased in the CI obesity group compared to all other groups." (PMID 28620170, 2017). "Its values, 9-77 min, fit the time interval, 5-180 min, of nonequilibrium in vitro conditions for our measurement of the kinetics of TBP's binding to each ODN corresponding to our three possible obesity-related SNP markers." (PMID 26694100, 2015). "During the past decades, β-actin (ACTB), glyceraldehyde-3-phosphate dehydrogenase (GAPDH), 18S ribosomal RNA (18S), ribosomal protein large P0 (RPLP0), and TATA box-binding protein (TBP) have been used extensively as reference genes in physiological status and diseases including obesity." (PMID 33330591, 2020).
Dystonia (4 papers, 2021 to 2025). An abnormally increased muscular tone that causes fixed abnormal postures. "Proband 6 (F6: II-1) presented with an SCA17 subtype characterized by dystonia (torsional spasm) and spastic paraplegia, carrying a TBP gene CAG/CAA repeat expansion of 41 repeats without concurrent STUB1 heterozygous mutations." (PMID 41001200, 2025).
Friedreich ataxia (4 papers, 2010 to 2023). An inherited condition that affects the nervous system and causes movement problems. "In European natives, pathogenic mutations should be searched in genes producing SCA1 (ATXN1), SCA2 (ATXN2), SCA3 (ATXN3), SCA6 (CACNA1A), SCA7 (ATXN7), SCA 12 (PPP2R2B), fragile X tremor ataxia syndrome (FMR1), SCA17 (TBP), CANVAS syndrome (RFC1), and Friedreich ataxia (FXN) [53﻿]." (PMID 35986227, 2023).
hereditary ataxia (4 papers, 2017 to 2026). An instance of an atactic disorder that is caused by an inherited genomic modification in an individual. "In patients with suspected hereditary ataxia, we identified expansions in loci that had not been assessed as part of routine diagnostic workup within the NHS at the time of recruitment, including ATN1, ATXN2, ATXN3, ATXN7, CACNA1A, FXN, TBP, and HTT." (PMID 35182509, 2022).
virus infection (4 papers, 2012 to 2021). "The binding affinity of TBP to the nuclear body area decreased upon viral infection while that of TFIIB slightly increased." (PMID 33996913, 2021). "ChIP-QPCR experiments were next performed to establish whether transient IFN-A gene expression correlated with the recruitment pattern of TATA-binding protein (TBP) to different IFN-A gene promoters following virus infection." (PMID 22685561, 2012). "Fluorescence recovery after photobleaching (FRAP) revealed accumulation of both TBP and TFIIB in the nuclear sub-compartment during viral infection." (PMID 33996913, 2021). "R443I virus infection showed relatively constant levels of Rpb1, Rpb2, TFIIB and TBP across the time course." (PMID 32032393, 2020).
acute leukemia (3 papers, 2017 to 2024). A clonal (malignant) hematopoietic disorder with an acute onset, affecting the bone marrow and the peripheral blood. "In order to identify the best reference genes for gene expression studies in peripheral blood and/or bone marrow samples of acute leukemia patients, a qPCR assay based on TaqMan detection for the expression analysis of the six selected genes (ACTB, ABL, GAPDH, HPRT, TBP and RPLP0) was used." (PMID 38397141, 2024). "Therefore, our study proposes the set of endogenous genes ACTB, ABL, TBP and RPLP0 as the most appropriate for the analysis of expression assays of acute leukemia samples." (PMID 38397141, 2024).
cervical cancer (3 papers, 2020 to 2025). A primary or metastatic malignant neoplasm involving the cervix. "In our previous study, TBP was shown to be responsible for the upregulation of METTL3 in cervical cancer cells." (PMID 39800682, 2025). "Further, the expression of TBP was significantly and positively correlated with the expression of Mettl3 in clinical cervical cancer patients from ChIPBase34, GEPIA, or TCGA database." (PMID 32444598, 2020). "Further, TATA-binding protein (TBP) can transcriptionally increase the expression of Mettl3 in cervical cancer cells via binding to its promoter." (PMID 32444598, 2020). "Using the online bioinformatics tools including GEPIA and Kaplan‐Meier plotter, we found that cervical cancer patients with increased expression of Mettl3 and TBP showed reduced disease-free survival (DFS)." (PMID 32444598, 2020). "Finally, we found that TBP can regulate the transcription of Mettl3 to increase its expression in cervical cancer cells." (PMID 32444598, 2020). "All these data suggested that TBP might be responsible for the upregulation of Mettl3 in cervical cancer cells via binding to its promoter-proximal site to increase the transcription." (PMID 32444598, 2020). "Western blot analysis showed that the expression of TBP, rather than NRF1, in cervical cancer cells was significantly greater than that in ECT1/E6E7 cells." (PMID 32444598, 2020).
colon carcinoma (3 papers, 2012 to 2017). "Compared to normal colon epithelium, TBP expression is elevated in the case of human colon carcinomas." (PMID 22496748, 2012). "Both Ras-dependent and Ras-independent mechanisms mediate the increases of TBP expression in colon carcinoma cell lines." (PMID 22496748, 2012). "Enhanced TBP expression is also observed in colon adenomas supporting the idea that increased TBP expression may be an early event in colon cancer development." (PMID 28415573, 2017). "Given the strong correlation between VEGFA and TBP expression in colon cancer, TBP expression may represent a novel biomarker." (PMID 28415573, 2017). "Furthermore, one of the datasets was comprised completely of adenomas, suggesting that enhanced TBP expression corresponds to an early event in colon cancer development." (PMID 28415573, 2017). "As our initial study showed that TBP expression was increased in several human colon cancer cell lines and tumors relative to normal, non-transformed cells, we further examined this in a larger patient population." (PMID 28415573, 2017).
colorectal cancer (3 papers, 2017 to 2023). A primary or metastatic malignant neoplasm that affects the colon or rectum. "A striking example is the TBP protein, which has been found overexpressed in colon and colorectal cancers." (PMID 31516394, 2019). "Collectively, these studies support the idea that increases in TBP expression contribute to enhanced VEGFA transcription early in colorectal cancer development to drive tumorigenesis." (PMID 28415573, 2017). "The finding that enhanced TBP expression is observed in a clinically significant population of human colorectal cancers supports the idea that TBP may function as an oncogene." (PMID 28415573, 2017).
melanoma (3 papers, 2016 to 2021). A malignant, usually aggressive tumor composed of atypical, neoplastic melanocytes. "ACTB, hypoxanthine phosphoribosyltransferase 1 (HPRT1), TATA-box binding protein (TBP) and transferrin receptor (TFRC) genes were reported to show a minimal average variation in FFPE and frozen tissue samples of melanoma and other diseases." (PMID 34940125, 2021). "In melanomas, TAFH RNAi induced the differential expression of TBP, TAF1, TAF2, TAF6, TAF10, and TAF12 ASVs." (PMID 27499390, 2016).
pancreatic cancer (3 papers, 2016 to 2024). "The level of ITCH and LATS1 expression were determined in 30 paired pancreatic cancer samples and matched adjacent, histologically normal tissues by qRT-PCR, and normalized to TBP expression (internal control)." (PMID 26621835, 2016). "In conclusion, this study uncovers a novel regulatory pathway in pancreatic cancer involving METTL16, MROH8, TBP, and m6A modifications." (PMID 39434688, 2024). "This study reveals a novel regulatory axis involving METTL16, MROH8, and TBP that modulates CAPN2 expression, contributing to the suppression of pancreatic cancer progression." (PMID 39434688, 2024).
serous ovarian carcinomas (3 papers, 2014 to 2023). "We sought to determine if the observed alterations in BDP1 in serous ovarian cancer are unique to BDP1 or are a common feature in all TFIIIB subunits including, BRF1, BRF2, and TBP which have been previously shown to be deregulated in cancer." (PMID 36305848, 2023).
cognitive decline (2 papers, 2012 to 2022). "Here we report on a family with an only marginally expanded CAG/CAA repeat in the TBP gene in which the proband presents with severe and rapidly progressing cognitive decline and only mild cerebellar symptoms." (PMID 22889412, 2012).
colitis (2 papers, 2017 to 2023). Inflammation of the colon. "In contrast, our comparative study of candidate reference genes suggested the use of TBP/Rplp0 as the appropriate reference genes for target gene normalization in C57BL/6 mice associated with DNBS- experimental colitis model." (PMID 28186172, 2017). "TbP and Eef2 were shown to be the reference genes of choice for RT-qPCR data normalization when assessing colonic inflammation using the DSS-experimental colitis model." (PMID 28186172, 2017).
colon adenocarcinoma (2 papers, 2016 to 2017). "The results are clinically relevant as TBP expression is significantly increased in both colon adenocarcinomas as well as adenomas relative to normal tissue." (PMID 28415573, 2017). "We next investigated whether changes in TBP expression could alter VEGFA expression in a transformed cell line using HT-29 human colon adenocarcinoma cells." (PMID 28415573, 2017).
depression (2 papers, 2022 to 2023). "Moreover, TBP and MEF2A were common transcription factors involved in three shared genes, which may play a significant role in ED and depression." (PMID 38111702, 2023).
Ewing sarcoma (2 papers, 2013 to 2021). A small round cell tumor that lacks morphologic, immunohistochemical, and electron microscopic evidence of neuroectodermal differentiation. "Remarkably, the expression in such tissues compared to the TBP housekeeping gene was more than 10-fold lower than the expression levels observed in Ewing sarcoma cell lines." (PMID 34830820, 2021). "Together with Ewing’s sarcoma (EWS) and RNA polymerase II, TATA box binding protein (TBP)-associated factor, 68 kDa (TAFII68/TAF15), FUS belongs to a family called TET or FET." (PMID 23577159, 2013).
glioma (2 papers, 2020 to 2025). A benign or malignant brain and spinal cord tumor that arises from glial cells (astrocytes, oligodendrocytes, ependymal cells). "TATA box binding protein (TBP), a transcription factor in the minor groove of DNA, is known to lead to DNA deformation and DNA unfolding is facilitated by the overhang of two phenylalanine residues of TBP triggering mitogenesis in glioma cells." (PMID 39941886, 2025). "Similarly, SP contains two phenylalanine residues at its C-terminus, being able to produce large-scale deformations in DNA and initiating transcription similar to that produced by TBP, producing mitogenesis in glioma cells, so essentially SP can be considered a transcription factor." (PMID 39941886, 2025).
hepatic cancer (2 papers, 2016 to 2021). "While TBP had the lowest expression stability in the three hepatic cancer cell lines." (PMID 34752497, 2021). "Moreover, for the studied cell lines, it is proposed that not to use ACTB and B2M; and TBP for normalizing the breast and hepatic cancer cell lines derived RT-qPCR data, respectively." (PMID 34752497, 2021).
neuroblastoma (2 papers, 2010 to 2024). Neuroblastoma (NB) is the most common solid, extracranial childhood tumor. "For 34 neuroblastoma samples, the proposed new algorithm yielded the smallest upper bound for the variance of the geometric mean of six genes, ACTB, B2M, GAPDH, HPRT1, TBP, and YWHAZ." (PMID 20470420, 2010).
stomach cancer (2 papers, 2015 to 2022). "We analyzed the relationship between the expression of ISGF-3, MZF1, SRF, and TBP and the prognosis of stomach cancer patients by the Kaplan–Meier plotter database." (PMID 35712475, 2022). "The results show that the expression of ISGF-3, TBP, MZF1, and SRF is significantly related to the survival of stomach cancer patients (ISGF-3: HR = 0.47, log-rank P = 1.1e-11; TBP: HR = 1.76, log-rank P = 5.5e-11; SRF: HR = 1.76, log-rank P = 5.5e-11; MZF1B: HR = 1.8, log-rank P = 1.7e-11)." (PMID 35712475, 2022).
adenoma (1 paper, 2017). A neoplasm arising from the epithelium. "Increased TBP expression in adenomas may produce a constitutive increase in VEGFA expression that then primes these tissues for a more robust VEGFA induction under hypoxic conditions to generate an angiogenic switch." (PMID 28415573, 2017).